L1CAM (L1 cell adhesion molecule)
Diseases named in the same sentence as L1CAM in open-access papers (continued):
Sharing a sentence is not in itself a finding about the gene and the disease.
glioma (continued). "The other type includes the fluorescence activated cell sorting and the magnetic activated cell sorting, which are based on glioma cell surface markers include CD133, CD15, L1CAM, Integrin α6." (PMID 24303074, 2013). "Similarly, IgSF members such as L1CAM (CD171), NCAM (CD56), PECAM-1 (CD31), ALCAM (CD166), and ICAM-1 (CD54) have been associated with metastatic progression in a range of cancers including melanoma, glioma, breast, ovarian, endometrial, prostate, and colon cancer." (PMID 22272201, 2012). "The neuronal cell adhesion molecule L1CAM (L1, CD171) is required for maintaining the growth and survival of CD133-positive glioma cells with stem-like properties." (PMID 22685459, 2012). "L1CAM, a neural adhesion molecule central to cell growth, survival, migration, and axon formation, is differentially upregulated in the CD133+ fraction of gliomas." (PMID 24212632, 2011). "The neural cell adhesion/recognition protein L1 (L1CAM; CD171) is abnormally expressed in multiple cancer cell types, including high-grade gliomas." (PMID 19874583, 2009). "In our study, L1 (L1CAM; CD171) expression was documented in high-grade human glioma surgical samples and proteolyzed L1 ectodomain was released into the media when these cells were cultured." (PMID 19874583, 2009). "Expression levels of the cell adhesion marker L1CAM were measured with flow cytometry to determine early effects of pharmacological treatment on low-grade gliomagenesis, as L1CAM has been shown to be upregulated in IDH1R132H astrocytes, and in IDH1R132H glioma patients (source: CGGA)." (PMID 40307935, 2025). "However, we observed a significant increase in the expression of stemness and malignancy markers such as CD133, L1CAM, Casp3, Nestin, and CD44 in surviving cells of both primary glioma and relapse cultures." (PMID 41304780, 2025). "Moreover, upregulation of L1CAM and CD44 expression in surviving glioma tumor cells that are detected after aptamer exposure is often associated with increased cell migration ability." (PMID 38256907, 2024). "L1 cell adhesion molecule (L1CAM) shRNA induced the elimination of CD133+ glioma cells, but it did not affect negative cells." (PMID 35205721, 2022). "Adhesion molecules, such as integrins, L1 cell adhesion molecule (L1CAM), cell division cycle 42 (CDC42), and ephrin-B2 (EB2), are required for the morphological changes occurring in glioma co-opting cells, leading to the emergence of a mesenchymal-like phenotype." (PMID 36294763, 2022). "Unlike ependymoma, L1CAM protein expression was not correlated with the C11orf95-RELA fusion gene in other gliomas, but it had correction with the patient age (older than 45-year-old, p = 0.006), ATRX mutation (p = 0.003) and Ki67 (p = 0.007)." (PMID 32509846, 2020). "The expression of L1CAM, in combination with CD133, defines a CSC population in glioma." (PMID 31952346, 2020). "Nevertheless, CSC-related functions, such as tumor initiation and self-renewal abilities, have not been defined yet by comparing L1CAM-positive and L1CAM-negative subpopulations of glioma cells." (PMID 32429448, 2020). "The self-renewal capacity and the tumorigenic potential of L1CAM-positive and L1CAM-negative subpopulations of glioma cells (even together with CD133) have not been characterized yet." (PMID 22685459, 2012).
glioma (continued). "Indeed, our interrogation of publicly available patient expression data from LGG patients confirmed a positive correlation between L1CAM and the predominant isoform GSK3B in IDHmut gliomas (source: CGGA) and showed that GSK3B is significantly upregulated in IDHmut glioma patients (source: CGGA)." (PMID 40307935, 2025). "Furthermore, L1CAM function in GBM cell migration was determined by the same group; ADAM10 would cleavage L1CAM ectodomain, which then would activate EGFR and integrins (FAK-mediated process) to promote glioma CSC migration." (PMID 33177991, 2020). "Together, these data suggest that L1CAM is required for maintaining the growth and survival of CD133+ glioma cells both in vivo and in vitro, and L1CAM may represent a GSC specific therapeutic target for improving the treatment of glioblastoma and possibly other brain tumors." (PMID 26880988, 2016). "Moreover, the role of an adhesion molecule of the immunoglobulin family in cancer stem cell is not unprecedented since L1CAM was recently shown to be required to suppress glioma growth of CD133+ cells in vitro and in vivo." (PMID 20219118, 2010). "Furthermore, it has not been determined whether L1CAM itself may have a prognostic value in gliomas and may be useful in immunohistochemical studies." (PMID 22685459, 2012). "In summary, L1CAM was found to be a significant marker in predicting the prognosis of glioma patients, but unlike ependymoma, it was not correlated with RELA in other gliomas." (PMID 32509846, 2020).
ovarian carcinoma (63 papers, 2011 to 2025). A malignant neoplasm originating from the surface ovarian epithelium. "L1CAM is also overexpressed in various types of human cancer, including gynecological tumors, such as ovarian cancer and EC, linked to poor prognosis, aggressive and invasive phenotype, advanced disease stages, metastasis, and resistance to chemotherapy." (PMID 41301764, 2025). "Future studies in a similar transgenic model using overexpression of L1CAM, instead of PTEN loss, would further support the role of L1CAM in ovarian cancer dissemination." (PMID 36509990, 2022). "Our data indicate that L1CAM is required for the expression of integrin ɑ5β1 and fibronectin; cell adhesion molecules that have been implicated in ovarian cancer cell survival and dissemination." (PMID 36509990, 2022). "The study on L1CAM+/CD133+ ovarian CSCs showed also, through the genetic manipulation of ovarian cancer cell lines, that L1CAM is causally involved in CSC-associated radioresistance as well as in self-renewal and tumor initiation." (PMID 32429448, 2020). "Eight loci (PABPC4L, APBA2, FAM189A1, FUT7, ENTPD2, NPDC1, C9orf139 and L1CAM) were associated with risks for both breast cancer and ovarian cancer (P<0.05)." (PMID 28145423, 2017). "Its expression in ovarian cancer has previously been studied using immunohistochemistry where the presence of L1CAM was associated with an adverse clinical outcome." (PMID 27174921, 2016). "The fibronectin receptor α5β1 also transduces the antiapoptotic effect of the adhesion molecule L1CAM (CD171), and L1CAM/CD171 is associated with poor prognosis in several cancers such as colon and ovarian cancers." (PMID 22567280, 2012). "The cell surface glycoprotein L1 cell adhesion molecule (L1CAM) is implicated in tumor progression and therapy resistance across various malignancies, including ovarian cancer (OC), and its overexpression is linked to enhanced cancer stemness and correlates with poor outcomes." (PMID 40429728, 2025). "L1CAM is implicated as an important factor that enables early fallopian tube cancer precursors to seed the ovary by promoting cell survival through extracellular matrix signaling, thereby facilitating ovarian cancer growth." (PMID 36509990, 2022). "Our results support the hypothesis that L1CAM promotes cell migration with formation and survival of multicellular aggregates, two phenotypes associated with early ovarian cancer dissemination from the fallopian tube to the ovaries." (PMID 36509990, 2022). "L1CAM is known to be associated with CD133 in ovarian cancer in a stem cell phenotype." (PMID 32374759, 2020). "In addition, the L1CAM was implicated in the chemoresistance of malignant tumor cells, including pancreatic ductal adenocarcinomas, glioblastoma multiforme, ovarian carcinoma, and anaplastic thyroid carcinoma." (PMID 25294816, 2014). "To investigate the role of L1CAM in ovarian cancer stemness and its contribution to therapy resistance, we generated L1CAM knockout (ΔL1CAM) HGSOC cells using CRISPR–Cas9 technology." (PMID 40429728, 2025). "Here, CRISPR–Cas9-mediated knockout of L1CAM in ovarian cancer OVCAR8 and OVCAR4 cells significantly impaired anchor-independent growth in soft agar assays and reduced clonogenic survival following external beam irradiation." (PMID 40429728, 2025). "Although soluble L1CAM (sL1CAM) has been detected in the serum and ascites of patients with epithelial tumors, such as EC and ovarian carcinoma, research assessing circulating protein levels remains limited." (PMID 41301764, 2025). "In vivo ovarian cancer models have shown that L1CAM expression promotes cancer stemness by enhancing spherogenicity, tumor take rate, self-renewal capacity, and tumor growth." (PMID 37566075, 2023).
ovarian carcinoma (continued). "The L1 cell adhesion molecule (L1CAM; CD171) has been reported as a poor prognostic marker in various solid tumors, including EC, colorectal cancer, gastric cancer, ovarian cancer, and breast cancer." (PMID 37835593, 2023). "In human patients with uterine and ovarian carcinomas, or pancreatic ductal adenocarcinoma, aberrant L1CAM expression was observed and accompanied by aggressive phenotype and tumor stages, making L1CAM a potential indicator of poor prognosis." (PMID 37893107, 2023). "When directly comparing immortalized FTSECs with ovarian cancer cell lines, we found that L1CAM was more highly expressed in the cancer cell lines." (PMID 36509990, 2022). "To begin deciphering the role of L1CAM in HGSC, we analyzed L1CAM expression in a panel of ovarian cancer cell lines by Western blot and found that all of the cell lines expressed detectable L1CAM protein." (PMID 36509990, 2022). "Since L1CAM is a cell adhesion molecule, we examined the contribution of L1CAM to the formation and maintenance of multicellular structures using the ovarian cancer cell line OVCAR8." (PMID 36509990, 2022). "In pancreatic and prostate cancer cells, L1CAM knockdown likewise significantly decreased migration and invasion, whereas overexpression of L1CAM augments motility and migration of ovarian carcinoma and gastric cancer cells in vivo." (PMID 34228897, 2022). "Overall, these data are consistent with the reported role of L1CAM in other solid tumors and indicate that L1CAM expression correlates with ovarian cancer progression." (PMID 36509990, 2022). "Overall, our results support the model whereby fallopian tube precursor cells utilize L1CAM to regulate integrin expression and signaling to support ovarian cancer dissemination to the ovary." (PMID 36509990, 2022). "Taken together these results indicate that L1CAM expression in ovarian cancer cells promotes cell-cell adhesion that supports multicellular cluster formation." (PMID 36509990, 2022). "Here, we use CAR T cells targeting the glycosylated CE7 epitope of the L1 cell adhesion molecule, L1CAM (formerly CD171), which is specifically expressed on tumor cells and a promising target for neuroblastoma and ovarian carcinoma." (PMID 34267756, 2021). "In addition, the L1 cell adhesion molecule (L1CAM), an axonal glycoprotein involved in neuronal migration and differentiation, was recently identified as an oncogene that is overexpressed in colon and ovarian cancers, and associated with increased invasion and poor prognosis." (PMID 34804909, 2021). "A study with 161Tb-labeled antibodies targeting the L1 cell adhesion molecule (L1CAM) in mice bearing ovarian cancer, showed high tumor uptake with low level of uptake in other organs." (PMID 34409048, 2021). "A study conducted on ovarian cancer cell lines revealed that L1CAM, in combination with CD133, marks a subpopulation of ovarian CSCs." (PMID 32429448, 2020). "Mechanistically, upon cisplatin treatment, L1CAM silencing partially prevented Akt activation, which was a key player in cisplatin resistance of ovarian cancer cells." (PMID 32429448, 2020). "Artificial overexpression of miR-34a in endometrial and ovarian cancer cells resulted downregulation of L1CAM expression and substantial reduction in cell migration." (PMID 32047551, 2020). "Anti-L1CAM antibodies, instead, have been widely used in preclinical models of ovarian carcinoma and other tumor types as radioimmunotherapy tools upon conjugation with different radioactive isotopes." (PMID 32429448, 2020). "In type-I ovarian cancer, often confined to the ovary and resulting in good prognosis, L1CAM was assayed in patients with either endometriod or clear cell histotype." (PMID 32429448, 2020). "Using fluorescence-activated cell sorting, specific cell populations expressing L1CAM alone or in combination with the established CSC marker CD133 were isolated from three ovarian cancer cell lines." (PMID 31952346, 2020).
ovarian carcinoma (continued). "In the context of gynecological oncology, the clinical utility of L1CAM has also been extensively studied in ovarian cancer (OC)." (PMID 32429448, 2020). "In ovarian cancer cells, the L1CAM gene was found to be under the regulation of TWIST1, a transcription factor that is causally linked to increased tumorigenicity as well as resistance to cisplatin." (PMID 32429448, 2020). "We demonstrated that the L1 cell adhesion molecule (L1CAM) is a new CSC target in ovarian cancer, triggering radioresistance." (PMID 31952346, 2020). "It is reported that L1CAM is related to the progression of several kinds of solid cancer, including ovarian cancer, colon cancer, gastric cancer, malignant melanoma, breast cancer, and pancreatic cancer." (PMID 32509846, 2020). "(C) AS of the human L1CAM exon 25 in seven EC batches purified and cultured from human ovarian carcinoma (HOC-ECs)." (PMID 30829570, 2019). "L1CAM-ECD stimulated the activation of ERK, FAK and Src and provided resistance against apoptosis and increased L1CAM-ECD in ovarian cancer patients correlates with increased chemoresistance." (PMID 31455004, 2019). "In ovarian cancer, L1CAM-ECD interacts with to α5β1, αvβ5, and αvβ3 integrins, and with NRP-1, the latter of which allows for binding the mesothelium." (PMID 31455004, 2019). "Other CARs mentioned in this review that use the CD28ζ costimulatory domain include L1CAM CARs for ovarian cancer in mice, MET CARs for MPM, MUC16 CARs in mouse models of ovarian cancer and peritoneal carcinomatosis, and NKG2D CARs in Ewing's sarcoma models." (PMID 30804938, 2019). "The cell adhesion molecule L1CAM is highly expressed in several human carcinomas and has recently been described as a new marker for endometrial and ovarian carcinomas." (PMID 29980240, 2018). "сhCE7 also inhibits the proliferation of L1CAM-positive tumor cells, namely, neuroblastoma, kidney carcinoma, colon cancer, and ovarian cancer." (PMID 30116755, 2018). "Altered expression of several CAMs, such as mucins, integrins, CD44, L1CAM, cadherin, claudins, EpCAM, ALCAM and METCAM/MUC18, is linked to the malignant progression of ovarian carcinoma." (PMID 30274262, 2018). "We have previously shown that the use of lutetium-177 labelled anti-L1CAM antibody chCE7 for RIT of ovarian cancer is suitable and a combination with paclitaxel improved the outcome." (PMID 30253737, 2018). "In ovarian cancer, the L1CAM cleavage intensity is a function of L1CAM surface expression and has been found to be a marker of poor progression-free survival and chemoresistance, although by itself it probably cannot rescue the cells from apoptosis." (PMID 27832351, 2017). "The objective of the study was to evaluate the level of soluble L1CAM in the sera of patients with endometrial and ovarian carcinomas and verify the feasibility of the sL1CAM as a marker of these carcinomas." (PMID 27832351, 2017). "Unfortunately, due to the small groups of patients, it was impossible to verify the correlation between the L1CAM concentration and endometrial or ovarian cancer histopathology." (PMID 27832351, 2017). "L1CAM expression is a marker of poor prognosis, short recurrence-free survival and advanced stage of the disease in many cancers including endometrial, ovarian carcinomas, pancreatic ductal adenocarcinoma melanoma and glioblastoma." (PMID 27832351, 2017). "L1CAM again has been found to be a potential marker of poor outcome, short time to relapse and platinum resistance in ovarian cancer patients." (PMID 27832351, 2017). "Such a role appears to be cell context-dependent: for example, L1CAM promotes cell-cell adhesion in normal ovarian surface epithelial cells while it stimulates cell motility in their transformed counterpart (i.e., ovarian carcinoma cells)." (PMID 28134764, 2017). "Numerous studies in preclinical models of different tumor types have indeed supported such a notion, particularly in ovarian cancer where L1CAM is often upregulated." (PMID 28134764, 2017).